TMPRSS2 (transmembrane serine protease 2)
Diseases named in the same sentence as TMPRSS2 in open-access papers (continued):
Sharing a sentence is not in itself a finding about the gene and the disease.
infection (continued). "Here, we examined receptor distribution in Syrian hamster lungs and correlated this distribution pattern of ACE2 and TMPRSS2 with the location of infection." (PMID 35255100, 2022). "Consistent with the current data, EVs expressing ACE2 inhibited the infection of pseudotyped lentiviruses from variants of concern of SARS-CoV-2, which was even more enhanced along with TMPRSS2." (PMID 36232549, 2022). "Our results are supported by the demonstration of co-existence of an MMP, TMPRSS2 infection pathway in HEC50B-TMPRSS2 cells." (PMID 36438831, 2022). "It is well known that furin and TMPRSS2 are important human enzymes that are employed by SARS-CoV-2 during the infection process." (PMID 35668062, 2022). "SARS-CoV-2-infection per se also increased TMPRSS2 expression, and pre-treatment of SARS-CoV-2-infected NHBEs with hydrocortisone further potentiated this effect." (PMID 35247068, 2022). "First, it can decrease the infection rate by downregulating TMPRSS2 protein expression, and second, reduce the pathogenicity, by suppressing SARS-CoV-2 replication." (PMID 36090095, 2022). "We observed a significant upregulation of HAT and Furin, especially KLK5, after infection, whereas TMPRSS2 and Matriptase were barely stimulated." (PMID 34826211, 2022). "The inhibition of longHR2_42 for VSV-SARS-CoV-2 occurred across several cell lines with different expression levels of the host cell proteases cathepsin and TMPRSS2 necessary for S-mediated infection." (PMID 36122200, 2022). "In our experiments, BriSΔ and WT SARS-CoV-2 both exhibited increased infection and replication in Vero E6/TMPRSS2 cells, but BriSΔ retained higher infection and replication rates as compared to WT virus." (PMID 35017512, 2022). "The normalized ACE2 and TMPRSS2 co-expression levels in the oral mucosa were similar to known sites of infection by SARS-CoV-2, i.e., nasal and intestinal epithelial cells." (PMID 35163355, 2022). "It has been reported that TMPRSS2 mutant mice have reduced the severity of lung pathology after infection with the original SARS-CoV." (PMID 34356843, 2021). "Enzalutamide reduced TMPRSS2 expression by inhibiting AR activity in LNCaP and VCaP cells, and significantly inhibited infection of these prostate cells by both authentic SARS-CoV-2 or SARS-CoV-2-S pseudovirus." (PMID 33558541, 2021). "In this context, however, it has been reported that cells expressing NRP1 alone only play a small part in SARS-CoV-2 infection, whereas its co-expression with ACE2 and TMPRSS2 greatly intensified infection." (PMID 33578849, 2021). "The data in this critical study demonstrated that through Notch-1/IL-6 signaling, anti-TNF-α agents decreased ACE2 expression and shedding through TMPRSS2/TACE modulation and increased the susceptibility to infection." (PMID 34025650, 2021). "SARS-CoV-2 was recently shown to bind to ACE-2 receptors for receptor-mediated endocytosis during cell infection using the TMPRSS-2 protein, which downregulates ACE-2 at the cell surface." (PMID 33732571, 2021). "Additional studies are needed to evaluate the expression of ACE-2 and TMPRSS-2 in placental cells in physiological and pathological conditions to investigate the infection and transmission of SARS-CoV-2." (PMID 34077991, 2021). "The titer began to increase 4 days after infection of VeroE6 cells, and the viral replication in VeroE6 cells was clearly slower than that in VeroE6/TMPRSS2 and HCT-8 cells." (PMID 33980675, 2021). "It was found that SARS-CoV-2 did not induce changes in the expression of ACE2 during the first 24 h of infection but significantly increased TMPRSS2 in Calu-3 cells." (PMID 34578229, 2021). "As the expression of TMPRSS2 is regulated by androgen, it can have a potential role in the male predominance of the infection." (PMID 34336361, 2021). "The immunostaining indicated ACE2+ and TMPRSS2+ cholangiocytes and the examination of SARS-CoV-2 genomic RNAs showed susceptibility of the cells to infection and increased viral load." (PMID 34760882, 2021).
infection (continued). "Transmembrane serine protease 2 (TMPRSS2) expressed on alveolar cells is involved in priming of S (spike) protein of SARS-CoV-2 that enhances the infection of other alveolar cells." (PMID 34680490, 2021). "IF analysis of sections and whole ALI lung constructs showed the presence of Spike protein in ACE2+TMPRSS2+ cells at the apical face, further confirming their infection with SARS-CoV-2." (PMID 34152044, 2021). "Next we examined the effect of TMPRSS2 on NCOA7-mediated inhibition of SARS-CoV-2 Spike pseudotype infection." (PMID 34807954, 2021). "In contrast, although the titers measured with CPE evaluation 4 days after infection using VeroE6/TMPRSS2 were slightly lower than the reference titer values, the CPE-based titers 5 days after infection were almost the same as the reference titer values." (PMID 33980675, 2021). "The increase in intracellular viral mRNA levels in CF cells exposed to flagellin, which indicates an elevated level of infection, is likely the result of the upregulated expression of TMPRSS2." (PMID 34950129, 2021). "Several antidepressants and antipsychotic drugs with different primary mechanisms of action were tested in ACE2/TMPRSS2-expressing human embryonic kidney cells against the infection by SARS-CoV-2 spike protein-dependent pseudoviruses." (PMID 35126106, 2021). "Transcriptional levels of the SARS-CoV-2 spike-processing host protease TMPRSS2 depend on infection time point and cell type." (PMID 34198973, 2021). "Fiege and colleagues also demonstrated that camostat, a broad-spectrum inhibitor of TMPRSS2 and related transmembrane serine proteases, potently suppressed infection of ALI cultures." (PMID 33901166, 2021). "The expression pattern of TMPRSS2 indicated a significant increase at the mRNA levels at both 24 h and 48 h post infection compared to mock-infected cells." (PMID 34325716, 2021). "Initially, we assessed enhancement conferred by increasing amounts of TMPRSS2 plasmid on ACE2-dependent infection." (PMID 34797899, 2021). "In this study, we investigated the variability in several pig genes (ACE2, ANPEP, DPP4 and TMPRSS2) that can serve as receptors or protease for priming the infection of coronaviruses." (PMID 33564056, 2021). "In Calu-3 cells that express the TMPRSS2, camostat completely blocked the Sfull infection, but E-64d had minimal effects, suggesting that Sfull preferentially enters Calu-3 cells via the plasma membrane fusion pathway." (PMID 33574281, 2021). "Our findings identified that HT and HD hindered the interaction between the S protein of SARS-CoV-2, hosted the cellular receptor ACE2 and downregulated the protein expression of ACE2 and TMPRSS2, thereby suppressing the infection with Vpp of SARS-CoV-2-S." (PMID 34444960, 2021). "Pre-existing liver and GI diseases not only have altered tissue expression and distribution of viral entry ACE2 receptor but also host protease TMPRSS2, which is required for both spike protein binding and cleavage to initiate infection." (PMID 34760721, 2021). "Immunofluorescent images showed that both of the two most important molecular adaptors associated with infection of SARS-CoV-2, ACE2 and TMPRSS2, were expressed in the oral epithelial cells." (PMID 34412632, 2021). "Genetic and pharmacological blockade of TMPRSS2 provided partial protection against SARS-CoV in mouse models of infection." (PMID 33596266, 2021). "The infection of HEK293T-ACE2-TMPRSS2 cell line by the pseudotyped lentiviruses was significantly reduced suggesting that these cells express TMPRSS2 and the activity of this protease is blocked by camostat mesylate." (PMID 35126106, 2021). "We also find the presence of host factors, ACE2, TMPRSS2, and AR, to overlap with the infection sites." (PMID 35602214, 2021). "In order to shed light on infectivity and permissiveness of the appointed cell lines in context of their ACE2/TMPRSS2 expression, we subjected cells to experimental infection with wildtype SARS-CoV-2." (PMID 34339474, 2021).
infection (continued). "The possibility of SARS-CoV-2 neurotropism, or the lack of it, is then analyzed with regard to the expression of the receptor (angiotensin-converting enzyme 2) or priming protease (transmembrane serine protease 2), and cellular targets of infection." (PMID 34835030, 2021). "Consistent with this, infection with these pseudotypes was only inhibited by camostat mesylate in the TMPRSS2 expressing cells." (PMID 34807954, 2021). "The intestinal brush border cells have high levels of TMPRSS2, transmembrane serine protease 2, which is capable of robust and persistent infection." (PMID 34768321, 2021). "Although the preferred pathway for infection is via the serine protease TMPRSS2 (early pathway), CatL, together with TMPRSS2, present tempting targets for pharmacological inhibition." (PMID 34941695, 2021). "This infection system uses VeroE6 cells stably overexpressing the TMPRSS2 gene, which is a member of type II transmembrane serine proteases." (PMID 33808940, 2021). "The results showed that the expression of ACE2 and TMPRSS2 in the cornea was high and the corneal organoids were permissive for virus entry and infection." (PMID 34760882, 2021). "The reduction in Caco2 infection by viruses produced in furin KO cells is consistent with the role of furin pre-cleavage in making the S2’ site accessible for TMPRSS2." (PMID 33493182, 2021). "With PV titers adjusted so that SARS1-PV and SARS2-PV infection were comparable in the presence of TMPRSS2, SARS2-PV transduced cells markedly less efficiently in its absence." (PMID 33465165, 2021). "Conversely, by maintaining low levels of ACE2 and TMPRSS2 and by exerting an anti-inflammatory effect, the KD can potentially attenuate the severity of infection and migration of SARS-CoV-2 to other ACE2-expressing tissues." (PMID 34684358, 2021). "To support our observation that TMPRSS2 can rescue infection from the suppressive effects of NCOA7 mediated endosomal acidification, we pharmacologically manipulated endosomal acidification and endo-lysosomal proteases." (PMID 34807954, 2021). "It has been demonstrated that the co-expression of NRP1 with ACE2 and TMPRSS2 markedly enhances the infection of SARS-CoV2." (PMID 34201505, 2021). "SARS-CoV-2 utilizes the entry receptor angiotensin-converting enzyme-2 (ACE2), with priming of the serine protease transmembrane serine protease 2 (TMPRSS2) to gain entry into the respiratory mucosa and cause active infection." (PMID 33068560, 2021). "Once attached, the host infection requires the expression of transmembrane serine protease 2 (TMPRSS2) for priming of the spike protein and viral entry into the cell." (PMID 34325716, 2021). "Our findings clearly show that SPINT2 regulates SARS-CoV-2 viral infection through the inhibition of TMPRSS2, since a drug induced inhibition of TMPRSS2 abrogates the infection-promoting effect of SPINT2." (PMID 34181691, 2021). "TMPRSS2 plays a dual role in the infection process as it also cleaves ACE2, which increases uptake of SARS-CoV and likely also SARS-CoV-2 virions." (PMID 33268377, 2021). "Recent studies have identified several key amino-acidic residues for S-protein interactions with the human ACE2 receptor and the TMPRSS2 membrane protease to initiate infection." (PMID 34201505, 2021). "Even though, and as expected, A549-cells expressing TMPRSS2 in addition to ACE2 allowed for higher infection rates, the antiviral activity of quinine was clearly detectable with a nearly complete block of infection at high concentrations." (PMID 33918670, 2021). "When TMPRSS2 overexpressed infection was compared to mock 293T-ACE2 cells, the enhancement of infectivity by TMPRSS2 for the P.1 variant was almost fourfold that for the D614G variant." (PMID 34645933, 2021). "By introducing additional gene copies of TMPRSS2 they have been rendered even superior to infection when compared to the parental cell line by 2-log." (PMID 34394046, 2021).
infection (continued). "Oral cavity expresses critical protein receptors such as ACE-2 and NRP-1 and enzymes such as TMPRSS2 required for viral entry and infection." (PMID 34749700, 2021). "who reported that TMPRSS4 besides TMPRSS2 enhances infection of small intestinal enterocytes with SARS-CoV-239." (PMID 33293627, 2020). "Studies also demonstrated that SARS coronavirus engages ACE2 as the entry receptor on the cell surface and employs the TMPRSS2 for Spike protein priming, which facilitates viral entry and infection." (PMID 33488611, 2020). "Since host genetic polymorphisms have been demonstrated to be associated with vulnerability to human infection, in this study five candidate genes—ACE2, TMPRSS2, CD209, IFITM3, and MUC5B—were selected based on their relevance to the current pandemic." (PMID 33101356, 2020). "Blocking of the host protease TMPRSS2, which is important for priming the fusion activity of the spike protein, also inhibited infection in lung cells." (PMID 32513797, 2020). "To further authenticate our pseudovirus, we tested infection of the human lung epithelial cell line Calu‐3 treated with TMPRSS2 inhibitors camostat and nafamostat (Fig EV1D)." (PMID 32944968, 2020). "Host cell infection can be blocked by a clinically proven inhibitor of the cellular transmembrane protease serine 2 (TMPRSS2), which is required for S protein priming of both coronaviruses." (PMID 33203141, 2020). "Our results revealed that ACE2 and TMPRSS2 were highly expressed in neonates compared with other populations, which imply the high incidence of infection." (PMID 33537060, 2020). "Expression of LY6E in the absence or presence of TMPRSS2 significantly inhibited the infection of all the COVpp, except for SARSpp, which was only significantly inhibited in the presence of TMPRSS2 expression." (PMID 32641482, 2020). "We surveyed the co-expression of SARS-CoV-2 entry genes ACE2 and TMPRSS2 throughout the GI tract to assess potential sites of infection." (PMID 32545271, 2020). "We show that ACE2 and TMPRSS2 coexpress in AT2 cells at the mRNA and protein levels, suggesting susceptibility to infection." (PMID 32971472, 2020). "Another serine protease inhibitor, nafamostat, inhibits MERS-CoV entry and infection by TMPRSS2 inhibition." (PMID 32604730, 2020). "The serine protease inhibitor camostat, which is a registered drug in Japan for gastroenterology problems, inhibits TMPRSS2 and confers partial resistance to infection with SARS‐CoV‐2, and total protection when combined with E‐64d, an inhibitor of CatB/L." (PMID 32573950, 2020). "Camostat mesylate has also significantly inhibited the TMPRSS2 in human lung Calu-3 cells and lowered the infection with SARS-CoV-2." (PMID 33664752, 2020). "The spike protein of SARS-CoV-2 binds with the ACE2 receptor and the protease TMPRSS2 mediates the infection process." (PMID 33055059, 2020). "Although NRP1 did not promote infection in HEK-293T cells, its coexpression with ACE2 and TMPRSS2 markedly enhanced infection." (PMID 33082293, 2020). "Recently, several porcine cell lines have been shown to be permissive to SARS-CoV-2 infection; in addition, single-cell screening studies showed that porcine ACE2/TMPRSS2 expression are compatible with infection." (PMID 33003988, 2020). "Similar to ACE-2 and TMPRSS2, the neuropilins are expressed abundantly in the respiratory and olfactory epithelium, becoming the nasal cavity epithelium, a key infection site for CNS infection." (PMID 33584720, 2020). "After experimental infection with SARS-CoV-2, TMPRSS2-deficient mouse strains showed reduced body weight loss and viral kinetics in the lungs." (PMID 32983181, 2020). "Similar to SARS-CoV, the entry receptor for SARS-CoV-2 was recently determined to be ACE2, with co-expression of transmembrane serine protease 2 (TMPRSS2) facilitating infection." (PMID 32887790, 2020).
infection (continued). "Furin-mediated cleavage was sufficient to propagate infection in pulmonary cells; however, TMPRSS2 and other proteases can facilitate fusion of infected and uninfected cells." (PMID 33142989, 2020). "When 293T cells expressing ACE2 were infected with SARS-CoV-2 pseudotyped viruses, treatment with E-64d reduced the infection by 90%, whereas when the cells additionally expressed TMPRSS2, the effect of E-64d nearly vanished." (PMID 33290397, 2020). "Here, we examine human pre-gastrulation embryos to determine the expression patterns of the genes ACE2, encoding the SARS-CoV-2 receptor, and TMPRSS2, encoding a protease that cleaves both the viral spike protein and the ACE2 receptor to facilitate infection." (PMID 32750256, 2020). "We estimated thus that in Vero cells expressing TMPRSS2, infection proceeded ~65% of the time via the TMPRSS2 pathway and ~35% via the Cathepsin B/L pathway." (PMID 33290397, 2020). "Higher ACE2 levels correlated with infection although TMPRSS2 and TMPRSS4 expression also showed a positive correlation as well." (PMID 32404436, 2020). "TMPRSS2 plays acritical role not only for SARS-CoV-2 infection but also for infection by othercoronaviruses and influenza." (PMID 32652001, 2020). "Here, we demonstrate that TMPRSS2 is able to cleave H2-HA in cell culture and that Tmprss2−/− mice are resistant to infection with a re-assorted PR8_HA(H2) virus." (PMID 32321537, 2020). "Tmprss2 knockout mice show reduced lung inflammation with IAVs (H1N1, H3N2, or H7N9) infection and exhibit decreased susceptibility to virus-induced morbidity/mortality." (PMID 33488611, 2020). "On the other hand, a significantly higher dose (EC50 around 30 μM) was required for VeroE6/TMPRSS2 cells, where the TMPRSS2-independent but cathepsin-dependent endosomal infection pathway likely predominates." (PMID 32532094, 2020). "We and others have previously shown that deletion of Tmprss2 in mice results in resistance to infection with H1N1 and monobasic H7N9 IAV." (PMID 30084768, 2018). "Here we report that the scaffolding tetraspanin protein CD9 links the receptor for MERS-CoV to a membrane fusion-activating protease called TMPRSS2, forming a complex that promotes rapid and efficient infection." (PMID 28759649, 2017). "Influenza-specific antibodies were readily detectable in sera of Tmprss2 knock-out mice after infection with PR8M and PR8F virus demonstrating that the inoculated virus was able to infect lung cells and elicit a humoral immune response." (PMID 24348248, 2013). "Infection of target cells with SARS-CoV S-pseudotyped virions is less sensitive to cathepsin inhibitors when target cells express TMPRSS2." (PMID 22816037, 2012). "SARS-CoV-2 may utilize alternative pathways of cell entry, involving cathepsin-dependent endocytosis, as demonstrated by infection of tissues with reduced expression of TMPRSS2." (PMID 41596537, 2026). "The infection process is initiated by the binding of the Spike protein to the angiotensin-converting enzyme 2 receptor and followed by the uptake of the viral protein by cellular proteases such as TMPRSS2, cathepsin L, and furin." (PMID 41596537, 2026). "In conclusion, co-localization of ACE2 and TMPRSS2 in oral and airway epithelia may explain the primary route of infection for SARS-CoV-2 virus." (PMID 40631549, 2025). "Both human ACE2 and TMPRSS2 expression was essential to support SC2 infection and replication." (PMID 40284950, 2025). "Akin to the infection assay in ACE2 single overexpression cells, the infectivity of VLP pseudotyped virus was respectively reduced 2.5‐, 10‐, and 3.3‐fold by the S371L, S371F, and S373P mutations when infecting ACE2 + TMPRSS2 overexpressing cells." (PMID 40062404, 2025). "Furthermore, a study investigates the spatial distribution of ACE2 and TMPRSS2 expression in the lung lobes of Syrian hamsters and its influence on the infection patterns of SARS-CoV-2." (PMID 39858469, 2025).